FOXK1 (forkhead box K1)
Diseases named in the same sentence as FOXK1 in open-access papers (continued):
Sharing a sentence is not in itself a finding about the gene and the disease.
renal fibrosis (1 paper, 2024). A final common manifestation of a wide variety of chronic kidney diseases characterized by glomerulosclerosis and tubulointerstitial fibrosis. "In the IRI‐induced renal fibrosis model, the gross renal morphology, results of histochemistry staining, and fibrotic marker expression levels were recapitulated and consistent with that in the UUO model, thus corroborating the pathogenic role of FOXK1 in renal fibrosis development in mice." (PMID 39083268, 2024). "In summary, we identified a novel fibrogenic factor in renal fibrosis progression, the transcriptional factor FOXK1, which emerged in a manner of proximal TEC‐specific distribution and cell‐state relevance of injured and failed repair." (PMID 39083268, 2024). "This study identifies FOXK1 as a critical glycolysis regulator that is expressed in renal tubular epithelial cells (TECs) during renal fibrosis." (PMID 39083268, 2024). "Herein, a new critical glycolysis regulator, the transcription factor forkhead box protein K1 (FOXK1) that is expressed in TECs during renal fibrosis and exhibits fibrogenic and metabolism‐rewiring capacities is reported." (PMID 39083268, 2024). "In this study, we aimed to investigate the role of FOXK1 in initiating glycolysis within TECs and renal fibrosis progression." (PMID 39083268, 2024). "Our findings showing that TECs‐specific deletion of the Foxk1 curbed the development of renal fibrosis enlighten the therapeutic potential of targeting FOXK1 in CKD treatment." (PMID 39083268, 2024). "In this study, we identified a novel fibrogenic factor, transcription factor FOXK1, which featured proximal tubule‐specific induction and a critical role in boosting glycolysis in TECs and promoting renal fibrosis." (PMID 39083268, 2024). "An elevated FOXK1 expression is necessary to turn on glycolysis in TECs and may lead to the development of renal fibrosis." (PMID 39083268, 2024). "We also explored the strategy of curbing renal fibrosis by FOXK1‐targeted gene silencing therapy." (PMID 39083268, 2024). "FOXK1 plays a pivotal role in bolstering the energic metabolism switch from FAO to glycolysis in TECs and aggravating the progression of renal fibrosis." (PMID 39083268, 2024).
Sepsis (1 paper, 2025). Sepsis is defined as life-threatening organ dysfunction caused by a dysregulated host response to infection.
serous ovarian cancer (1 paper, 2019). "In contrast to the small gene set (IGF2BP1, SRF, FOXK1 and PDLIM7), the enlarged gene set (35 genes plus IGF2BP1 and SRF) was significantly associated with poor OS probability in serous ovarian cancer, HCC as well as LUAD, as supported by HR values ranging from 1.52 to 2.15." (PMID 30371874, 2019).
Ureteral obstruction (1 paper, 2024). Obstruction of the flow of urine through the ureter. "To determine the role of FOXK1 in CKD progression, we first analyzed the single‐cell RNA sequencing dataset, GSE190887, related to mouse unilateral ureteral obstruction (UUO) and unilateral ischemia‐reperfusion injury (uni‐IRI) that was deposited in the Gene Expression Omnibus (GEO) database." (PMID 39083268, 2024).
viral infection (1 paper, 2015). "In contrast, FOXK1 (parent gene of KLHL2P1) is downregulated only in early viral infection (a >1.5-fold decrease in expression and downregulation in all nine datasets at 12 h and six datasets at the 24-h time point)." (PMID 26426037, 2015).
Wilms tumor (1 paper, 2021). An embryonal neoplasm characterized by the presence of epithelial, mesenchymal, and blastema components. "Five of seven proven candidates, PEG10, YEATS2, FOXK1, CBLL1 and MCRS1 showed a clear positive correlation of mRNA levels with MYCN in Wilms tumors undergoing the SIOP protocol." (PMID 34689785, 2021).
tumor (47 papers, 2016 to 2026). "Previous studies have shown that FoxK1/2 is closely associated with various diseases and plays a complex role in tumor therapy especially." (PMID 35903069, 2022). "We found that were strongly present FOXK1-positive signals were present in the nucleus and cytoplasm of cancer cells (primary cancer tissue) and tumor-associated stroma cells (TAS)." (PMID 27223064, 2016). "Then, we put forward the hypothesis that the tumor-promoting effect of FOXK1 might be associated with the Akt/mTOR signaling pathway." (PMID 32363163, 2020). "Considering that FOXK1 was reported to be associated with M2-type macrophages attraction and thus promoted tumor growth, the HUMT/YBX1/FOXK1 axis might also be functioning in immune escape." (PMID 32138762, 2020). "Of note, FOXK1 has also been implicated in suppressing tumorigenesis in models of breast cancer, indicating that tumour suppression might be a conserved function within FOXK family members." (PMID 30897782, 2019). "By downregulating FOXK1, miR-16-5p significantly suppresses angiogenic activity and tumor expansion." (PMID 41561226, 2026). "We demonstrated that the inhibition of the FOXK1/AKT signaling pathway via miR-155-5p is an essential mechanism by which circ_0079226 enhances tumor metastasis in GC." (PMID 39981141, 2025). "Corresponding with the downregulation of circ_0079226, an increase in E-cadherin protein level and a reduction in FOXK1, N-cadherin, and vimentin levels were observed in the tumor tissues." (PMID 39981141, 2025). "FOXK1 is involved in decreasing the epithelial marker E-cadherin and increasing mesenchymal markers such as vimentin, thereby, aiding tumor cell invasion in GC." (PMID 39981141, 2025). "As expected, the protein level of FOXK1 was significantly upregulated in the kidneys of obstructive nephropathy compared with para‐tumor." (PMID 39083268, 2024). "GEPIA assessment of the correlation between expression of the 15 differentially expressed FOXs (DE-FOXs) in the TCGA PAAD data set and the pathological stage of PAAD patients revealed a significant association between FOXK1, FOXQ1, and FOXP1 and tumor stages." (PMID 36622275, 2023). "Analysis of the promoter methylation levels of the 15 DE-FOXs by UALCAN revealed downregulation of the promoter methylation levels of FOXD1, FOXJ1, and FOXK1 in tumor tissues." (PMID 36622275, 2023). "In the present study, upregulation of FOXK1 was detected in ESCC cells and tissues, which was associated with tumor stage and poor prognosis." (PMID 37173384, 2023). "A former study clarifies the high expression of FOXK1 in NSCLC, and FOXK1 is available to expedite tumor growth in vivo." (PMID 35220908, 2022). "More importantly, it has been revealed that FOXK1 plays pivotal roles in tumor initiation and progression." (PMID 35065674, 2022). "The correlation between CHEK1, CDC25A, FOXK1 and tumor-infiltrating immune cells in the LIHC microenvironment was evaluated by using TIMER." (PMID 35309118, 2022). "At the post-transcriptional level, IGF2BP1 maintains the expression of multiple SRF target genes, including PDZ and LIM domain 7 (PDLIM7) and forkhead box K1 (FOXK1), which further enhances tumor cell growth and invasion." (PMID 34692544, 2021). "Guo and Wang revealed the role of miR-329-3p as a suppressor of HCC cell proliferation, invasion, migration, and EMT processes as well as tumor growth by downregulating FOXK1 and inhibiting the AKT/mTOR pathway." (PMID 34307695, 2021). "The relative mRNA level of FOXK1 was significantly higher in tumor tissues compared with that in their adjacent non-tumor tissues (p = 0.0026)." (PMID 32363163, 2020). "Twenty-eight days after orthotopic transplantation, we found that the inhibition of FOXK1 reduced the number of metastases and tumor weight in the gastric wall." (PMID 32268297, 2020). "The result showed that depletion of FOXK1 significantly inhibited xenograft tumor formation and growth." (PMID 32363163, 2020).
tumor (continued). "We further confirmed in the tumor that HUMT-KO significantly downregulated FOXK1 expression by qRT-PCR." (PMID 32138762, 2020). "In support of findings presented here, analyses in EOC-, HCC-derived and other cancer cells indicate that the transcriptional regulator FOXK1 promotes the proliferation and metastatic potential of tumor cells in a conserved manner." (PMID 30371874, 2019). "Not only the tumour-suppressive role of E1A, but also of E6 proteins from human papillomaviruses 21/14, is likely to depend on concomitant targeting of FOXK1 and FOXK2 via a conserved Thr-Ser-containing motif." (PMID 30897782, 2019). "A stable transfectant of FOXK1 promoted migration, metastasis and dissemination, thereby facilitating tumor development and progression in GC cells." (PMID 27882939, 2016). "FOXK1 and c-jun expression were correlated with tumor progression and represented significant predictors of overall survival in GC patients." (PMID 27882939, 2016). "Our results indicate that c-jun has a critical role in FOXK1-mediated tumor growth, EMT and metastatic phenotypes in vitro and in vivo." (PMID 27882939, 2016). "In conclusion, FOXK1 is markedly overexpressed in GC and enhances tumorigenicity and tumor growth in vivo." (PMID 27882939, 2016). "The FOXK1-stable transfectant group exhibited a significantly increased proliferation rate and tumor vessel density compared with the vector group, whereas c-jun knockdown inhibited the growth rate and tumor vessel density in the FOXK1-overexpressing group." (PMID 27882939, 2016). "On the contrary, tumours derived from the downregulation of FHL2 in FOXK1-overexpressed cells were markedly smaller than those of the FOXK1-treated mice from 15 to 30 days." (PMID 27892920, 2016). "To test the role of c-jun in FOXK1-mediated tumor progression, we injected cells into nude mice via the tail vein, which results in lung metastasis within 40 days." (PMID 27882939, 2016). "Stable transfectant of FOXK1 promoted migration, metastasis, and dissemination, thus facilitating tumor development and progression in CRC cells." (PMID 27223064, 2016). "Coupled with the morphologic changes of EMT, the knockdown of FOXK1 decreased the invasive ability of tumor cells." (PMID 27223064, 2016). "The discovery of FOXK1 may provide a new therapeutic strategy for overcoming tumor resistance by intervening in the glycolysis pathway." (PMID 40842594, 2025). "IGF2BP1 promotes SRF expression in a conservative m6A-dependent manner by impairing the decay of SRF mRNA guided by miRNA, thereby promoting the expression of genes such as PDLIM7 and FOXK1 that can promote tumor cell growth, ultimately promoting tumor cell growth and invasion." (PMID 39062595, 2024). "According to the clinicopathological features, high expression levels of FOXK1 (the expression level of FOXK1 in tumor tissues was higher than that in corresponding normal tissues by 200%) were associated with TNM stage, invasion depth, and lymph node metastasis." (PMID 37173384, 2023). "In vivo, FOXK1 overexpression increased tumor volume, microvessel density, and metastasis." (PMID 37174744, 2023). "We speculate that in CRC, tumor-suppressive tRFs impair the stability of FOXK1 mRNA and subsequently lead to the inhibition of Wnt/β-catenin signaling involving epithelial-to-mesenchymal transition (EMT)." (PMID 35065674, 2022). "This suggested that circEHD2 promoted NSCLC tumor growth by regulating miR-3186-3p /FOXK1 axis." (PMID 35220908, 2022). "FOXK1 induces the Wnt/β‐catenin pathway and consequently regulates tumor genesis and progression." (PMID 35166053, 2022). "Overall, Foxk1/2 has dual functions in tumors, acting as either an oncogene or a tumor suppressor." (PMID 35903069, 2022). "We also performed in vivo experiments to verify that FOXK1 can inhibit tumor metastasis." (PMID 32268297, 2020).
tumor (continued). "To further determine the role of FOXK1 in GC tissues, we assessed whether the silencing of FOXK1 inhibits the lung partialization of diffuse GC cells in vivo and established a mouse tumor model via tail vein injection." (PMID 32268297, 2020). "Furthermore, IHC staining showed that cell proliferation marker Ki-67 was decreased in FOXK1-depleted tumor tissues." (PMID 32363163, 2020). "Recently, accumulating evidences showed that FOXK1 was upregulated in various tumor tissues and might participate in the tumorigenesis." (PMID 32363163, 2020). "The xenograft model showed that HUMT-KO could significantly suppress tumor growth compared with the control group, and it could be reversed by FOXK1 overexpression." (PMID 32138762, 2020). "PDLIM7 and FOXK1 promote tumor cell growth and were reported to enhance cell invasion." (PMID 30371874, 2019). "We knew that RUFY3 or FOXK1 has been correlated with the malignant of tumor cells." (PMID 28623323, 2017). "Recent progress has highlighted the significance of FOXK1 in tumor progression." (PMID 28623323, 2017). "Furthermore, RUFY3 and FOXK1 expression were correlated with tumor progression and represented significant predictors of overall survival in CRC patients." (PMID 28623323, 2017). "The tumour volumes of the FOXK1-overexpressed cells were markedly larger than those of the vector." (PMID 27892920, 2016). "Moreover, the elevated expression of FOXK1 was showed to be correlated with tumor progression and was a significant predictor of overall survival in CRC patients." (PMID 27223064, 2016). "The FOXK1 stable transfectants group showed a significant increase in the proliferation rate and tumour vessels compared with those observed in the vector group, whereas the knockdown of FHL2 inhibited the growth rate and tumour vessels in the FOXK1-overexpressed group." (PMID 27892920, 2016). "However, xenografted tumor growth was suppressed in mice that were injected with FOXK1-overexpressing cells in which c-jun was downregulated compared with FOXK1-overexpressing cells with normal c-jun levels." (PMID 27882939, 2016). "Furthermore, this study of FOXK1 is the first to indicate the contribution of EMT to tumor metastasis and the invasion of CRC cells in vitro and in vivo." (PMID 27223064, 2016). "Kaplan-Meier analysis of the survival curves showed a significantly worse overall survival for patients whose tumors had high FOXK1 levels (log-rank test P=0.000), indicating that high FOXK1 tumor protein level is a marker of poor prognosis for patients with CRC." (PMID 27223064, 2016). "FOXK1 promoted tumor metastasis through EMT program induction." (PMID 27223064, 2016). "These strong correlations suggest that FOXK1 overexpression may promote tumor invasion and metastasis." (PMID 27223064, 2016). "Therefore, we investigated whether FOXK1 exerts the tumor-promoting functions via Akt/mTOR signaling pathway." (PMID 32363163, 2020). "Additionally, we also found that inhibition of FOXK1 attenuated the migrative and invasive ability of GBC cell lines in vitro and in vivo, indicating that FOXK1 might be involved in tumor metastasis, which happens very early in GBC patients." (PMID 32363163, 2020). "The abnormal expression of FOXK1 may have an important role in tumour development." (PMID 27892920, 2016). "Two GRNs, albeit comprising a smaller number of tumor cells, showed high activity for the TCF7L2 regulon (along with KLF8, FOXK1, FOXP2, BACH1) (labeled TCF7L2+) and CTCF (along with MAFG and NR1H) (labeled CTCF+) respectively." (PMID 38645034, 2024). "The top GRNs in primary tumors were TCF4, TAGLN2, FOXK1, and BHLHE41, whereas the top upregulated GRNs in recurrent tumor cells were FOXP2, FOXD1, SIX4, and HMGB1." (PMID 39711559, 2024). "Based on public database analysis, strong positive correlations between FOXK1 and ZSWIM4 mRNA levels were observed in OC tumor tissues." (PMID 38383406, 2024).
tumor (continued). "Two GRNs, albeit comprising a smaller number of tumor cells, showed high activity for the TCF7L2 regulon (along with KLF8, FOXK1, FOXP2, and BACH1) (labeled TCF7L2+) and CTCF (along with MAFG and NR1H) (labeled CTCF+), respectively." (PMID 38968122, 2024). "In addition, FOXK1 has been found to be upregulated in many malignant tissues and induces tumor proliferation and metastasis, and the oncogenic roles may be partly due to its involvement in the positive regulation of the cell cycle as well as its induction of EMT17–20." (PMID 37173384, 2023). "Recently, forkhead box k1 (FOXK1), a member of the FOX transcription factor family, has been reported to be correlated with tumor progression in multiple malignancies." (PMID 32363163, 2020). "In this study, we confirmed that inhibition of FOXK1 decreased the GBC cell proliferation and tumor growth by a series of in vitro and in vivo assays." (PMID 32363163, 2020). "To further validate the role of FOXK1 in HUMT-mediated tumor progression, we transfected MDA-MB-231 and BT549 cells stably overexpressing HUMT or empty vector with si-FOXK1 or scramble vector." (PMID 32138762, 2020). "After adjustment, tumor size, tumor differentiation, AJCC stage, FOXK1 expression and c-jun expression were identified as covariates." (PMID 27882939, 2016). "Compared with the FOXK1-overexpressing cells, the FHL2 downregulation observed in FOXK1-overexpressing cells led to a significant reduction of visible tumours in the liver and lung, which correlated to a lower number of metastasis loci." (PMID 27892920, 2016). "In multivariate analysis, tumour differentiation, AJCC stage, FOXK1 expression and FHL2 expression each had significant prognostic value for overall survival." (PMID 27892920, 2016). "The broad cancer-promoting functions of FOXK1 warrant further investigation to characterize the significance of this colocalization of PLK1 and FOXK1 and to determine what role it may play in tumor progression." (PMID 37174744, 2023). "Besides, the protein levels of FOXK1, β‐catenin, cyclin D1, and c‐Myc were downregulated in shRNASEH1‐AS1‐transfected tumor xenografts." (PMID 35166053, 2022). "Finally, in vivo tumor formation and metastasis were evaluated to show the effect of the SNHG1-mediated miR-376a/FOXK1/Snail axis." (PMID 34095464, 2021). "Western blot analyses indicated that both RUFY3 and FOXK1 were significantly upregulated in the nine of ten examined tumor samples compared with the paired adjacent noncancerous tissues from the same patients." (PMID 28623323, 2017). "EMT is reportedly induced by various signals in the tumor microenvironment, including TGF-β1.26, 27 We aimed to explore whether FOXK1 is involved in TGF-β1-induced EMT in GC cells." (PMID 27882939, 2016). "SNHG1 competitively binds to miR-376a and inhibits the expression of miR-376a, thereby promoting FOXK1 and Snail expression, leading to reduction of HCC cell proliferative, migrating, and invasive properties, and promotes cell apoptosis and promotion of tumor growth and metastasis in HCC." (PMID 34095464, 2021). "The negative correlation between DLC1 and MMP9 expression in a relatively low percentage of cases could be due to the great heterogeneity between tumor samples that may harbor other genetic and/or epigenetic factors to alter the regulatory relationship between DLC1/FOXK1 and MMP9." (PMID 32214200, 2020). "However, the effects of the interaction between RUFY3 and FOXK1 on EMT and tumor invasion/metastasis for CRC remain unknown." (PMID 28623323, 2017). "However, the molecular mechanism by which FOXK1 synergizes with FHL2 tumour proliferation, EMT and metastasis is not well defined." (PMID 27892920, 2016). "Among these 87 patients, FOXK1 or FHL2 expression in tumour samples was found to be significantly correlated with tumour differentiation, lymph node metastasis, TNM stage, serosal invasion and tumour size; however, it was not correlated with gender, age or location." (PMID 27892920, 2016).